DUSP1 (dual specificity phosphatase 1)
Diseases named in the same sentence as DUSP1 in open-access papers (continued):
Sharing a sentence is not in itself a finding about the gene and the disease.
tumor (continued). "DUSP1, a phosphatase that regulates MAPK signaling, is involved in cellular responses to stress and inflammation, and its downregulation may repress tumor cell survival under adverse conditions." (PMID 41411347, 2025). "Finally, as for malignant peripheral nerve sheath tumours (MPNSTs), knock down (KD) of DUSP1 and/or DUSP6, which are highly expressed in these tumours as compared to normal tissue, leads to reduced MPNST cell growth and to increased ERK1/2 phosphorylation." (PMID 40943262, 2025). "In addition, the downregulation of DUSP1 significantly correlated with a higher Gleason score, pre‐treatment prostate‐specific antigen (PSA) levels, and tumor progression in patients." (PMID 38962952, 2024). "The favorable toxicity profile of BCI, its selectivity for DUSP1 and DUSP6, and the ability to inhibit tumor cell proliferation promote further investigation to determine whether this compound targets TAMs and tumor cells." (PMID 38139370, 2023). "SLC38A2, DUSP1, and FGF7 expressed predominantly in tumor sites than that in normal lung in previous studies; however, they were expressed predominantly in the tumor stroma in this study." (PMID 36505794, 2022). "Microarrays and RNA-seq cohorts also validated a decreasing trend of DUSP1 at mRNA levels in OVCA tissues via a large sample size (n of OVCA = 936, n of non-tumour = 214), which was also observed in peripheral blood of OVCA patients (n of OVCA = 74, n of healthy women = 47)." (PMID 35911442, 2022). "Under microscope, IHC staining illustrated that no high expressions of DUSP1 protein were found in OVCA tissues but rather in non-tumour tissues; the difference was considered statistically significant (IHC cohort-1, p < 0.0001; IHC cohort-2, p = 0.0011)." (PMID 35911442, 2022). "Dual-specificity phosphatase 1 (DUSP1), a two-way specific Sue/tyrosinase, is involved in inactivating different MAPK family isoforms, and it plays an indispensable role in cell cycle arrest and cell proliferation in tumor and normal cells." (PMID 35741797, 2022). "DUSP1 and DUSP6 both exhibit tumor suppressor and tumor promoter activity in different cancers, and the same phosphatases may exhibit opposite roles in different tumors." (PMID 36589747, 2022). "DUSP1 downregulation increased JNK1/2 phosphorylation without further inhibiting the tumorigenicity of NEU PKR+/+ tumor cells in SCID mice." (PMID 31086176, 2019). "Inhibition of DUSP1 by the shRNAs did not significantly impact on eIF2α-P indicating that the phosphatase acts downstream of eIF2 in the NEU tumor cells." (PMID 31086176, 2019). "In NSCLC cancer cell lines where DUSP1/MKP-1 was constitutively expressed, siRNA knockdown increased cisplatin sensitivity some 10 fold, reduced the growth of these cell lines in nude mice and rendered the resulting tumours cisplatin sensitive." (PMID 30401534, 2019). "In the early phase of cancer, the upregulation of DUSP1 enables tumors to evade SAPK-induced death, while in the advanced stages of cancer, the downregulation of DUSP1 promotes cell proliferation, increases tumor growth, and actuates the metastatic process." (PMID 31767833, 2019). "On the other hand, the variable effects of JNK and p38 MAPKs on NB cell apoptosis endorse the possibility of a beneficial use of inhibitors of JNK- or p38-specific MKPs, such as DUSP1, DUSP8, DUSP10, or DUSP16, but only in NB cases in which the activity of JNKs or p38s favors tumor chemosensitivity." (PMID 30866462, 2019). "Moreover, expression of some PTP tumor suppressors, such as PTPRD, PTPRO, PTPN12, PTPN13 and DUSP1, is reduced due to epigenetic silencing." (PMID 29558404, 2018). "Moreover, when we divided the tumor samples into two groups according to tumor stage (Group I (AJCC stage I and II) and Group II (AJCC stage III and IV)), we found that DUSP1 levels were lower in Group II." (PMID 28129656, 2017).
tumor (continued). "Moreover, DUSP1 is exclusively expressed in HER2+ carcinomas, which are relatively poor prognosis tumours but amenable to HER2-targeting therapies, and DUSP1 expression is associated with an increased risk of metastasis and shorter overall survival." (PMID 26859151, 2016). "The result is particularly interesting in the context of (a) cancer, as many cancers show increased expression of DUSP1 and reduced expression of DUSP2, and (b) tumor related conditions such as hypoxia, where low oxygen levels upregulate DUSP1 and downregulate DUSP2." (PMID 23060802, 2012). "By extension, re-establishing DUSP1 levels—either through CEBPB inhibition or direct DUSP1 upregulation—might represent a viable strategy to restore controlled MAPK signaling and reduce tumor aggressiveness." (PMID 41411347, 2025). "Mechanistically, DUSP1 inhibits tumor growth by modulating pERK/MAPK-MMP2 signaling pathway and tumor metastasis by suppressing vascular endothelial growth factor (VEGF) expression, suggesting DUSP1 regulation may be an interesting therapeutic target for GBC metastasis." (PMID 41158869, 2025). "Resting tumour cDC1s included cluster 5 enriched in transcripts involved in the unfolded protein response (UPR) such as Creld2, Hspa5, and Pdia6, as well as the clusters 2, 3 and 6 that expressed transcripts such as Fos, Jun, and Dusp1 and cluster 0 that expressed H2afz, Lyz2, Sub1." (PMID 40745918, 2025). "In addition, DUSP1 and SDC2 exhibited an increase in macrophages in the tumor microenvironment." (PMID 39871942, 2024). "Additionally, corin treatment with or without PLX4032 led to increased expression of H3K4Me2, H3K27Ac, DUSP1, and DUSP5, as well as increased expression of markers of apoptosis and tumor hypoxia in BRAFi-R tumors, with associated decreases in the expression of both MITF and AXL." (PMID 38300709, 2024). "However, there has been no study involving the regulation relationship of EPHA2 and DUSP1 in any tumor." (PMID 37057290, 2023). "Although expression of DUSP1 did not reveal significant deference in tumor tissues between patients with and without cachexia, we cannot confirm whether DUSP1 in skeletal muscle was regulated by tumor-derived factors." (PMID 36387242, 2022). "Interestingly, in two very recent studies, CDKN2B-AS1 have been investigated as a tumor oncogene (upregulated) which regulates cell proliferation and inhibit apoptosis in CRC through sponging miR-28-5p and targeting MAPK inactivator dual-specificity phosphatase 1, respectively." (PMID 35907803, 2022). "DUSP1 is a kind of phosphatase and can negatively regulate the activation of JNKs, ERKs, and p38 MAPK, which plays an important role in the regulation of the human cell growth cycle and tumor genesis and development through signaling pathways such as the MAPK pathway." (PMID 35401213, 2022). "Our results from RNA-seq with the in vitro and in vivo findings suggested that CBD might induce the expression of DUSP1 and KLF6, following the HNSCC tumor suppression via the DUSP1 and/or KLF6 dependent activation of apoptosis and autophagy cellular signaling on HNSCC." (PMID 33244087, 2020). "LINC01111 exerts its tumor suppressive effects via the inactivation of the stress-activated protein kinase/c-Jun NH2-terminal kinase (SAPK/JNK) signaling pathway by upregulating a related gene, dual specificity phosphatase 1 (DUSP1), which inhibits SAPK/JNK phosphorylation." (PMID 31767833, 2019). "Thus it is likely that elevated expression of DUSP1/MKP-1 in tumours can mediate chemoresistance and this is supported by studies in non-small cell lung cancer (NSCLC) where overexpression of DUSP1/MKP-1 is observed and patients become resistant to treatment with cisplatin." (PMID 30401534, 2019).
tumor (continued). "Although less well studied than DUSP1/MKP-1, there have nevertheless been numerous reports of either increased or reduced expression of DUSP4/MKP-2 in a wide variety of human cancer cell lines and primary tumours including pancreatic, lung, ovarian, breast, liver, thyroid and colon." (PMID 30401534, 2019). "On the other hand, other studies report that canonical NOTCH pathway is needed for the tumorigenesis of KRASG12V driven NSCLC and that pharmacological inhibition with GSI arrests tumor growth partly via activation of DUSP1 and consequent dephosphorylation of ERK specifically (not MEK)." (PMID 30464927, 2018). "The RAS/RAF/MEK/ERK pathway also consists of proteins which are considered as oncogenes, e.g., RAS, RAF and other proteins which may have tumor suppressor activities e.g., protein phosphatase 2A (PP2A), dual specificity protein phosphatase 1 (DUSP1) and others." (PMID 29348885, 2017). "Moreover, the anti-tumor effects of combined Gefitinib and MPA treatment are mediated by DUSP1." (PMID 29383165, 2017). "Noticeably, the tumor suppressor proteins whose levels have been shown to be downregulated by SKP2-dependent degradation in various tumor types, including p27, p57, Dusp1, and Rassf1A were not decreased in liver lesions from SKP2/N-RasV12 and SKP2/myr-AKT1 mice." (PMID 25537506, 2015). "In addition, DUSP1 knockdown markedly attenuated PCC proliferation and tumor angiogenesis." (PMID 24409315, 2014). "Other genes in the area include PDGFRB, which plays an important role in tumor neovascularization, TGFBI, PTTG1, DOCK2 and DUSP1 (the latter three genes were speculated based on our internal studies), which were likely to be involved in ccRCC progression and development." (PMID 20671976, 2010). "The upregulation of DUSP1 by tumour-supporting genes has also been described in a study performed in TNBC MDA-MB-231 and MDA-MB-468 cells, showing that β2-adrenergic receptor, which may act as a protumoural gene, determines an increase in DUSP1 and a reduction of ERK1/2 phosphorylation." (PMID 40943262, 2025). "It was observed that three key FRGs (ALB, ATF3, and DUSP1), which were differentially expressed between renal tubular tissues with and without FSGS in patients receiving tumor nephrectomy, conformed to the predicted results." (PMID 38368317, 2024). "Immunohistochemical staining for DUSP1 in 47 tumor samples from GBC patients and 25 samples of normal gallbladder tissue indicated lower expression levels in tumor tissues." (PMID 28129656, 2017). "Both facts might explain the observation that qPCR results only revealed trends, not significant changes, in the expression levels of DUSP1, CYR61, SLC6A14 and DUOX2 in tumor ischemic colorectal tissue samples." (PMID 26222051, 2015).
cancer (150 papers, 1973 to 2026). A tumor composed of atypical neoplastic, often pleomorphic cells that invade other tissues. "The expression levels of DUSP1 are closely associated with the clinical prognosis of various cancers." (PMID 40489463, 2025). "Aberrant DUSP1 regulation is implicated in modulating cancer cell resistance to chemotherapy and radiotherapy, as well as facilitating immune evasion within the TME." (PMID 41158869, 2025). "DUSP1 was also observed to be an oncogene associated with drug resistance during cancer intervention." (PMID 36276279, 2022). "This is in accord with a range of other studies where BCI causes cancer cell cytotoxicity via apparent inhibition of DUSP1 or DUSP6." (PMID 35478300, 2022). "The protein encoded by DUSP1 is a phosphatase with dual specificity for tyrosine and threonine and is a potential target for cancer therapy in humans." (PMID 33846360, 2021). "For cancer related genes, Nav3, Cenpf, Muc5Ac, Mpp7, Gas1, MageD2, Dusp1, Ros, Polr2a, Rragd, Ros1, and Hoxa9 are mutated." (PMID 32793490, 2020). "Further mutations in cancer-related genes included Nav3 (V1129L), Cenpf (D1327E), Muc5ac (A429P), Mpp7 (Q158R), Gas1 (G326R), Maged2 (A473S), Dusp1 (C24R), Ros1 (W1875C), Polr2a (M1102I), Rragd (L385P), and Hoxa9 (insertion of “G” in UTR)." (PMID 32793490, 2020). "The mechanism underlying the oncogenic function of DUSP1 in these cancers is probably due to DUSP1-medaited inhibition of JNK activation and subsequent escape from JNK-induced apoptosis of the cancer cells." (PMID 29558404, 2018). "Studying the relationship between DUSP1 and cancer‐associated inflammation provided a new perspective to explore its role in carcinogenesis." (PMID 27227569, 2016). "Together, we concluded that DUSP1 methylation is a cancer-associated hypermethylation event." (PMID 28220843, 2017). "Thus, DUSP1 methylation is a cancer-associated hypermethylation event that is closely linked with triple-negative status." (PMID 28220843, 2017). "In the next section, we will review the potential regulatory role of DUSP1 in cancer and discuss the potential of DUSP1 as a pharmacologically targetable entity." (PMID 41158869, 2025). "In human cancers, DUSP1 controls MAP kinase activity, and particularly the MAPKs ERK pathway involved in cancer development and progression." (PMID 41158869, 2025). "DUSP4 is one of the most closely related enzymes of the well characterized DUSP1, and its role in cancer progression gained importance in the last decade." (PMID 40943262, 2025). "Radiation therapy plays a crucial role in the treatment of human cancer, and high expression of the MAPK phosphatase DUSP1 is found in many cancers, leading to radioresistance." (PMID 41158869, 2025). "Dysregulation/downregulation of DUSP1 in advanced stages of cancer disproportionately activates MAPK pathway activity, thereby impacting the response to oncologic therapies." (PMID 41158869, 2025). "DUSP1 not only induced chemotherapy resistance but also modulated radiation resistance in various cancers by targeting JNK-induced decreased apoptosis." (PMID 41158869, 2025). "Additional lines of evidence have been collected in support of an antitumoural role of DUSP1 in other types of cancer." (PMID 40943262, 2025). "Collectively, these studies suggest that the dysregulation of DUSP1 expression in different stages of cancer makes targeted therapy complicated, and DUSP1 levels modulate and affect chemotherapy, radiotherapy, and immunotherapy efficacy." (PMID 41158869, 2025). "DUSP1 is one of the first discovered and most studied DUSPs, and its role in cancer has been extensively investigated." (PMID 40943262, 2025). "In the next section, we review the functional role of DUSP1 in various cancers to understand the significance of this protein in cancer progression or suppression." (PMID 41158869, 2025).
cancer (continued). "Because DUSP1 expression regulates several cellular signaling pathways in several types of cancers, the interference of DUSP1 in chemotherapy is studied in detail." (PMID 41158869, 2025). "As most cancers are treated using a combination of chemotherapy, radiation, and/or immunotherapy, when evaluating DUSP1 as a therapeutic target, it will be critical to examine the interactions between these current oncologic approaches and DUSP1 inhibition." (PMID 41158869, 2025). "DUSP1 has a complex and well-recognised role in cancer, as a regulator of MAPK, autophagy, cell proliferation and differentiation." (PMID 40438247, 2025). "In ferroptosis research, DUSP1 expression increases upon ferroptosis induction in cancer cell lines." (PMID 40823304, 2025). "Concerning a possible role of DUSP1 in the support of cancer aggressiveness, it has also been reported that this DUSP supports drug resistance." (PMID 40943262, 2025). "MAPK phosphatase DUSP1 plays an important role in regulating the functions of the MAPK family in cancer cells." (PMID 38758860, 2024). "This agrees with the phenotype that we observed in lung and that was observed in other cancer types, where DUSP1 expression increases early during tumorigenesis and prevents JNK-mediated apoptosis." (PMID 38951654, 2024). "Lnc-FAM84B-4 interacts with HNRNPK, promoting cancer progression by suppressing the expression of the MAPK phosphatase DUSP1." (PMID 38238853, 2024). "Our findings revealed that DUSP1 was the most significantly and widely enriched gene in pan-cancer MRD." (PMID 38627863, 2024). "We found that Tgfb3 colocalized with Dusp1 which is known as a crucial participator in multiple diseases and cancers." (PMID 36820224, 2023). "Several studies have demonstrated the involvement of DUSP1 in malignant tumor progression through various signaling pathways." (PMID 37503331, 2023). "Despite the prominent mechanisms of the MAPK pathway in cancer, the role of DUSP1 in cancer still remains controversial." (PMID 35627105, 2022). "DUSP1 is expected to be a specific target in cancer cachexia for preventing and treating muscle atrophy." (PMID 36387242, 2022). "In post-treatment tumors, genes such as FOS, JUNB, COL1A2, and DUSP1 have shown to favor cancer proliferation and invasion and were predominantly expressed compared with pre-treatment tumors." (PMID 36505794, 2022). "A Spearman’s correlation analysis demonstrated the clinical significance of DUSP1 related to cancer cachexia." (PMID 36387242, 2022). "DUSP1 has garnered significant attention from gynaecologists because of its effective performance in the treatment of other cancers." (PMID 35911442, 2022). "Together, our results show DUSP1 plays a role in suppression of LINE-1 transcription in cancer cells." (PMID 34425899, 2021). "Our application of the C-BERST method identified both known and novel LINE-1 transcriptional regulators, including the dual specificity phosphatase, DUSP1, in cancer cells." (PMID 34425899, 2021). "Dual-specificity protein phosphatase 1 (DUSP1) has been shown to inhibit cancer progression through the SAPK/JNK signaling pathway." (PMID 34692482, 2021). "As in PC3, most noteworthy genes positively correlated with this principal component are ZFP36 and DUSP1, both are known for their function of regulation in cancer progression." (PMID 32231683, 2020). "Consistently, both sustained ERK activation and decreased DUSP1 protein levels are observed in cancer cells." (PMID 31151270, 2019). "For example, in some cancers, DUSP1 is overexpressed and is considered responsible for the failure of JNK-driven apoptotic pathways induced by chemotherapeutics; i.e., adjunct therapeutics with a DUSP1 inhibitor would have merit." (PMID 31316508, 2019). "The ontological analysis revealed a role of these miRNAs in cancer progression, vascular invasion and cancer immune surveillance thought the regulation of DUSP1, PD-L1 and MUC1." (PMID 31164669, 2019).